EGFR (epidermal growth factor receptor)
Diseases named in the same sentence as EGFR in open-access papers (continued):
Sharing a sentence is not in itself a finding about the gene and the disease.
tumor (continued). "Taken together, our data suggest that NPM1 is required for WNT-driven intestinal cell proliferation and tumor initiation; this dependency persists after oncogenic KRAS activation, which drives resistance to epidermal growth factor receptor and mTOR inhibition." (PMID 41413654, 2026). "In multivariate analysis, right-sided tumor location remained a strong predictor of VTE (OR 5.2; 95% CI 1.9-14.1; p = 0.001), along with anti-EGFR therapy." (PMID 41751211, 2026). "Peptide ligands can be designed to target receptors overexpressed in tumor tissue (e.g., luteinizing hormone–releasing hormone (LHRH) receptor, integrin αvβ3, epidermal growth factor receptor [EGFR]), angiogenesis markers, or BBB receptors." (PMID 41590805, 2026). "In summary, our study uncovers a crucial finding that DC maturation is markedly restricted within the TME of EGFR‐mutant NSCLC, which we identified as a significant barrier to effective anti‐tumor immunity." (PMID 41144813, 2026). "Receptor‐mediated delivery has also been achieved using ligands for epidermal growth factor receptor (EGFR) or integrins such as αvβ3, which mediate tumor invasion." (PMID 41126784, 2026). "In this study, we identified a novel mechanism of immune escape in EGFR‐mutant NSCLC, focusing on the critical role of DCs in anti‐tumor immunity." (PMID 41144813, 2026). "Some CNAs overlapped between tumor types, others were tumor type-specific; losses of CDH20 and PTEN were observed in both tumor types, whereas amplifications seemed more tumor type-specific, such as EGFR and MAP2K4 in colon cancer and ERBB2 in breast cancer." (PMID 41537310, 2026). "In tumor progression, S100A4 interacts with key signaling mediators such as EGFR and β-catenin, which are critically involved in keratinocyte differentiation and follicular proliferation." (PMID 41596498, 2026). "This analysis revealed significantly elevated DCBLD1 expression in both EGFR WT and EGFR Mut LUAD tissues compared to adjacent non-tumor tissues." (PMID 41522352, 2026). "Among the representative phosphatases of EGFR, PTP1B exhibits particularly complex regulatory patterns, functioning as both a tumor suppressor and promoter." (PMID 41522352, 2026). "This study evaluates the role of NF-κB and EGF receptors (EGFR, HER3) in tumor aggressiveness among Moroccan patients." (PMID 42221598, 2026). "Genes associated with MAPK signaling cascades, a major downstream pathway of EGFR signaling (AREG, JUN, DNAJB1, DUSP1), were upregulated in tumor C0 NK cells." (PMID 41082397, 2026). "Because EGFR-TKI treatment alters the tumor microenvironment, biomarkers predictive of ICI response are ideally identified post-EGFR-TKI resistance, but obtaining repeat biopsies at this time can be challenging." (PMID 41825931, 2026). "Combined EGFR inhibition and NOX4-mediated ROS suppression would provide synergistic anti-tumor effects in resistant cancers." (PMID 41562694, 2026). "In nude mice with overexpression of EGFR-bearing tumors, PDA-Dox-Pc-QRH achieved tumor-targeted delivery, effectively inhibited tumor growth under light, and even resulted in complete tumor ablation." (PMID 41355972, 2026). "The application of F127ZIF‐8AB680 in EGFR‐mutant NSCLC represents an innovative approach to overcome the limitations of current CD73 inhibitors, whose effects are compromised by poor tumor penetration and rapid clearance from the body." (PMID 41144813, 2026). "These factors regulate epithelial-mesenchymal transition and angiogenesis, interact with epidermal growth factor receptor/KRAS pathways to influence tumor invasion and promote chemotherapy resistance by sustaining tumor stemness." (PMID 41268614, 2026). "Through analysis of clinical tumor samples, genetic manipulation, and functional assays, we identify the lysosomal protein LAPTM4B as a key driver of EGFR-TKI resistance by enhancing EGFR phosphorylation and downstream signaling." (PMID 41362742, 2026).
tumor (continued). "Tumor cell killing assays in co-cultures with PBMCs showed that the Db-TriTE performed equally well to the bispecific control, taFv-EGFR on c-MET-/EGFR+ SW480 cells." (PMID 41552759, 2026). "In xenograft mouse models bearing EGFR+ TNBC, 177Lu‐T‐AuNP exhibited high tumour uptake and subsequent tumour inhibition, thereby prolonging the survival time of the experimental mice." (PMID 41555955, 2026). "Dysregulated kinase signaling particularly involving EGFR, PI3K/AKT/mTOR, MAPK, and ALK pathways drives tumor growth, survival, and metastasis." (PMID 41821616, 2026). "Among these, dysregulation of the epidermal growth factor receptor (EGFR), BRAF, and HER2 signaling pathways represents a central driver of tumor progression and therapeutic resistance." (PMID 41899309, 2026). "We stratified the TCGA-LUAD dataset based on EGFR mutation status and observed significantly elevated DCBLD1 expression in both EGFR WT and EGFR Mut LUAD tissues compared to adjacent non-tumor tissues." (PMID 41522352, 2026). "By restoring the DC maturation and enhancing their capacity to prime CD8+ T cells, this approach reprograms the TME of EGFR‐mutant NSCLC, fostering more effective anti‐tumor immune responses than the traditional drug delivery method." (PMID 41144813, 2026). "At the tumor margin, miR-22 inhibited Rho GTPase signaling, toll-like receptor signaling, trans-Golgi network budding, cell interactions, VEGF, EGFR signaling, and cell cycle signaling, among others." (PMID 41540504, 2026). "Enhancing the sensitivity of tumor cells to apoptosis by treatment with BCL2 inhibitors, such as ABT737, or other apoptosis inducers can effectively overcome EGFR-TKI resistance." (PMID 41281943, 2025). "Previous studies have similarly identified reduced infiltration of TILs in EGFR mutant tumor tissues, which is consistent with the inadequate number of CD8+ T lymphocytes in EGFR mutant LUAD in the present study." (PMID 40130724, 2025). "EGFR amplification, occurring in 80–90% of HNSCC cases, drives ligand-independent receptor phosphorylation, a critical event in tumor progression." (PMID 40362183, 2025). "According to the transcriptomic analysis of EGFR-mutant NSCLC tumor cells HCC827 and HCC4006 before and after the development of EGFR-TKI resistance, 380 common upregulated DEGs (logFC > 2, adjusted P < 0.01) were selected." (PMID 40510028, 2025). "It is particularly noteworthy that in EGFR-mutant NSCLC models, the combination of anti-HDGF antibodies and osimertinib not only achieved complete or near-complete tumor regression but also markedly prolonged progression-free survival." (PMID 41278276, 2025). "We employed targeted next-generation sequencing to analyze seven actionable driver genes - EGFR, KRAS, NRAS, BRAF, ALK, ROS1, and PIK3CA - in formalin-fixed, paraffin-embedded tumor specimens from Vietnamese NSCLC patients." (PMID 40502411, 2025). "Specifically, miR‐146a‐5p has been reported to bind directly to WNT2, EGFR, NOTCH2, TRAF6, IRAK1 and EIF5A2 to inhibit EMT and act as a tumour suppressor in various human cancers." (PMID 40785027, 2025). "•In patient-derived tumor organoid models, FER controls MET and EGFR oncogenic signaling required for invasion in 3D Collagen-I extracellular matrix." (PMID 41115375, 2025). "According to preclinical research, the EGFR and VEGF (vascular endothelial growth factor) signaling pathways work together to promote tumor growth." (PMID 40361442, 2025). "In contrast, the group characterized by EGFR amplification and unmethylated MGMT had the highest rate of marginal recurrences (24.2%), potentially indicating a locally infiltrative tumor phenotype." (PMID 40722305, 2025). "Transcriptome analysis shows increased expression of many pro-tumor pathways upon expression of IDH1 R132Q versus R132H, including transcripts of EGFR and PI3K signaling pathways." (PMID 40188944, 2025).
tumor (continued). "Since HCC827 tumor is sensitive to EGFR inhibitors, both control and CMTM4 KO tumor growth were significantly inhibited after gefitinib treatment." (PMID 39948411, 2025). "EGFR comutation was more common in ERBB2amp than in ERBB2mut NSCLC (12.0% vs. 4.9%) and infrequent in other tumor types." (PMID 40178042, 2025). "Biomarkers can indicate alterations in signaling pathways, for example, changes that are critical for cancerous cell growth, as in the case of EGFR or PI3K activity, representing a druggable target activity necessary for tumor growth and survival." (PMID 40141854, 2025). "In contrast, ursodeoxycholic acid (UDCA) exerts antagonistic effects: it not only downregulates EGFR expression and suppresses EMT, but also inhibits tumor metastasis by enhancing epithelial cadherin expression." (PMID 41357193, 2025). "We set up a 3-way co-culture of T-cells, macrophages, and MDA-MB-231 tumour cells expressing EGFR, then exposed the co-culture to a T-cell engager (TCE) targeting EGFR." (PMID 41309950, 2025). "Through SRB assays, colony survival assays, and spheroid formation, we found that when combining them with EGFR-TKI, they displayed an enhanced inhibition of tumor cell proliferation when compared with single drugs in the resistant cells." (PMID 41281943, 2025). "Notably, in ultraselect patients with right-sided tumors characterized by specific gene alterations (RAS/BRAF/EGFR ectodomain wild type), early tumor shrinkage and depth of response may serve as prognostic markers for chemotherapy plus anti-EGFR antibody treatment." (PMID 40280867, 2025). "In multiple xenograft cancer models, HCB101 induced significant inhibition of tumor growth as a single agent and showed synergistic anti-tumor effects when combined with anti-HER2 or anti-EGFR monoclonal antibodies." (PMID 41131565, 2025). "A major driver is receptor tyrosine kinase (RTK) signaling, particularly via the epidermal growth factor receptor (EGFR), which is overexpressed in 80–90% of HNSCC cases and signals downstream through PI3K, AKT, and mTOR to fuel tumor growth." (PMID 41375018, 2025). "The activity of MEKs, MAPKs, and ELK1 was found significantly suppressed and xenografts studies also revealed that tumor growth was limited as well, indicting a direct link between ELK1’s deactivation by EGFR blocking and antitumor effects." (PMID 40862737, 2025). "Simultaneously, it induces tumor cell apoptosis and inhibits proliferation through pathways such as PI3K/YAP1/TAZ, PI3K/Akt, EGFR, and NF-κB, demonstrating high safety." (PMID 41156537, 2025). "Targeted therapies, including inhibitors for pathways like EGFR and PI3K/mTOR, have shown some promise, though challenges persist due to tumor heterogeneity and resistance mechanisms." (PMID 39796773, 2025). "Several CAR-T cell therapies are targeting EGFR, MUC1, and mesothelin (MSLN), and other tumor antigens and are being tested in early-phase clinical trials." (PMID 41373672, 2025). "LncMLETA1 facilitates tumor metastasis via regulating EGFR and IGF1R expression and its level in patient plasma is correlated with tumor metastasis and a higher TNM stage, indicating its potential as a prognostic biomarker for metastasis of lung cancer." (PMID 39937018, 2025). "Thus, EGFR inhibitors (Erlotinib/Tarceva, Osimertinib) could block cancer cell signaling, preventing the proliferation and survival of cells with wild-type EGFR, and affect the tumor GPC." (PMID 40979445, 2025). "In this study, we found that hypoxia significantly decreased the sensitivity of EGFR-mutant LUAD cells to osimertinib, highlight the complexity of the tumor microenvironment in drug resistance." (PMID 41145422, 2025). "To further investigate the role of STARD4 in the activation of EGFR/PI3K/AKT pathways, we detected the protein level of p-EGFR, p-PI3K, and p-AKT in the tumor tissues from the xenograft nude mice model." (PMID 40831538, 2025).
tumor (continued). "For instance, curcumin, a natural antioxidant, has demonstrated enhanced anticancer effects when combined with EGFR inhibitors in preclinical models of non-small cell lung cancer (NSCLC), helping to overcome tumor resistance." (PMID 40563308, 2025). "Gefitinib, a small molecule EGFR inhibitor, in combination with IFN-α, delayed tumor growth in a HNSCC xenograft model." (PMID 41511327, 2025). "PYCR1 stabilizes EGFR by facilitating its deubiquitination and simultaneously promotes TLR-mediated NF-κB activation, demonstrating its multifaceted role in tumor progression." (PMID 41254241, 2025). "With HNSCC driven by EGFR aberrations, all three CDX models exhibited sustained tumor growth control by TAVO412 even after treatment cessation." (PMID 39995668, 2025). "miR-145 directly targets EGFR (Epidermal Growth Factor Receptor) and NUDT1 (Nudix Hydrolase 1), thereby inhibiting downstream oncogenic signaling pathways, mainly EGFR/PI3K/AKT, and suppressing tumor growth." (PMID 41465462, 2025). "SHP2 inhibitors have shown promise in preclinical studies of EGFR-mutant and ALK fusion-positive tumours with activation of MAPK pathway." (PMID 40849356, 2025). "Similar results were observed with IT injection of EGFR‐targeted LNPs encapsulating GFP mRNA, showing higher GFP expression in CD44‐tumor cells compared to naked LNPs or isotype‐LNPs." (PMID 39736115, 2025). "In this tumor, copy number variation (CNV) analysis showed that MDM4 amplification dominates the malignant clones, which additionally have either EGFR or PDGFRA amplifications, resulting in increased ChrAcc around these genes." (PMID 38724668, 2025). "In particular, BiTEs are designed to recruit and activate cytotoxic T cells by simultaneously binding to a tumor antigen, such as EGFR or MET, and the CD3 receptor on T cells, facilitating targeted activation and tumor cell lysis." (PMID 41303538, 2025). "TSPAN1 can activate PI3K/AKT and EGFR/MAPK/ERK signaling pathways, enhancing tumor cell proliferation." (PMID 40777026, 2025). "In contrast, molecularly targeted therapies (e.g., EGFR, VEGFR, and FGFR inhibitors) and the incorporation of circulating tumor DNA (ctDNA) or next-generation sequencing remain investigational approaches, currently limited to clinical trials." (PMID 41300892, 2025). "In particular, dysregulation of tyrosine kinase receptors, such as epidermal growth factor receptor 1 (ERBB1/EGFR) and epidermal growth factor receptor 2 (ERBB2/ErbB2) activates key signaling pathways involved in tumor cell proliferation and metastasis." (PMID 40689167, 2025). "Using multiplexed Opal fluorophores, we simultaneously evaluated five markers: CMTM6, EGFR, RAB11, DAPI (a nuclear dye), and Pan Cytokeratin (to discern tumor versus stromal cell identity)." (PMID 40521789, 2025). "We reported pre‐clinical evidence for successful and prolonged tumor growth inhibition in HNC achieved by Cas9 mRNA and guide against SOX2 administered intratumorally via EGFR‐targeting LNPs." (PMID 39736115, 2025). "Several signaling pathways promote cell proliferation and tumor growth, including PI3K/Akt/mTORC1, Ras/Raf/ERK, EGFR, FGFR, HER2, and CDK4/6." (PMID 41375062, 2025). "In addition, AREG works as a key amplifier of EGFR signalling, being able to integrate signals from other low-affinity EGFR ligands at the receptor state, generating multiple signalling modalities that induce pathological processes such as fibrotic disorders and tumour invasion." (PMID 40868999, 2025). "Activated EGFR initiates several signaling pathways, including the ERK and STAT3 pathways, which promote cell proliferation, tumor progression, and survival." (PMID 40881676, 2025). "The resistance mechanisms between EGFR and CD73 pathways remain poorly understood, as our study focused primarily on the role of CD73 in tumor cells." (PMID 40191718, 2025).
tumor (continued). "According to the literature, heat at a certain range often induces tumor growth of HCC by activating MET and EGFR signals, extracellular collagen I-mediated ERK signal, or VEGF/VEGFR1 signal." (PMID 41173836, 2025). "Although anti-EGFR treatment inhibits EGFR, the downstream RAS-RAF-MEK-ERK is constitutively active, leading to persistent tumor growth." (PMID 40940822, 2025). "PRMT1 significantly contributes to chemoresistance in TNBC by altering the methylation of key molecules like epidermal growth factor receptor (EGFR) and phosphoglycerate dehydrogenase (PHGDH), which strengthens tumor resilience." (PMID 40927753, 2025). "The third-generation CD47-SIRPα inhibitor HCB101 significantly inhibits tumor growth as monotherapy and demonstrates synergistic anti-tumor effects with anti-HER2 or anti-EGFR monoclonal antibodies." (PMID 41417432, 2025). "The combination treatment inhibited the EGFR/JAK/STAT3 signaling pathway and reduced PD-L1 expression, concurrent with increased immune-mediated tumor cell death through the perforin/granzyme B pathway." (PMID 40347254, 2025). "In recent years, Chimeric Antigen Receptor (CAR) T-cell therapy has revolutionized hematologic cancer treatment by genetically modifying T cells to target tumor-specific antigens like CD19, CD70, BCMA, EGFR, and HER2, leading to high remission rates." (PMID 40312353, 2025). "Automated MRI segmentation improved the accuracy; EGFR therapy increased the ADC, and reduced the tumor size." (PMID 41150754, 2025). "Secretion levels of fibroblast growth factors, including EGFR, VEGF, TGFB1, and PDGF-BB, were decreased in the medium of CNPY3-knockdown cells, indicating a potential paracrine effect of CNPY3 on the tumor stroma." (PMID 40055606, 2025). "Overexpression of USP6NL stabilizes EGFR, enhancing AKT signaling, tumor cell survival, and therapy resistance." (PMID 40565099, 2025). "designed EGFR‐CAR NK cells targeting EGFR and oncolytic herpes simplex virus (oHSV), which can selectively replicate in and ultimately lyse tumor cells." (PMID 40859900, 2025). "In preclinical models, EGFR-targeted tyrosine kinase inhibitors quickly suppress PI3K-AKT, MAPK/ERK signaling in tumor cells, preventing tumor cell lines from proliferating in Swiss albino mice." (PMID 41304988, 2025). "These pathways often intersect with key oncogenic signals such as EGFR, MAPK, PI3K/AKT, and STAT3, contributing to tumor progression and therapeutic resistance." (PMID 40868244, 2025). "Crizotinib and erlotinib (an EGFR inhibitor) showed synergistic effects in orthotopic tumor model mice, and it is tempting to propose the combination of Crizotinib and erlotinib in patients with HGFR+/EGFR+ GBM." (PMID 40358199, 2025). "The patient was treated with Osimertinib, a third-generation epidermal growth factor receptor (EGFR) tyrosine kinase inhibitor (TKI), as well as definitive local therapy for primary and metastatic sites, resulting in significant tumor reduction." (PMID 39902235, 2025). "For instance, studies have demonstrated that following EGFR-TKI therapy, tumor cells transition into a drug-tolerant persistent state, characterized by distinct gene expression profiles, including the upregulation of the anti-apoptotic protein BCL-XL." (PMID 40003951, 2025). "VEGF, TGF-β, CXCR4, Cav-1, Wnt7a, EGFR and EPHA2 enhance vascular formation and influence tumor microenvironment dynamics." (PMID 40486870, 2025). "Our BsAb was created under the premise that EGFR and VEGF-A would be effective therapeutic targets, as they modulate pathways that promote tumor growth, angiogenesis, and metastasis in OC." (PMID 40969763, 2025).